APP (amyloid beta precursor protein)
Diseases named in the same sentence as APP in open-access papers (continued):
Sharing a sentence is not in itself a finding about the gene and the disease.
Obesity (51 papers, 2012 to 2025). Accumulation of substantial excess body fat. "IXA4, the most selective IRE1α-XBP1 activator, can promote the degradation of Alzheimer’s disease-associated amyloid precursor protein (APP) mutants, prevent APP-associated mitochondrial dysfunction, and remodel obesity-induced metabolic dysfunction." (PMID 35765067, 2022). "The most significant finding of our work was that chronic alcohol feeding or obesity causes a major decline in hepatic LRP1 levels while substantially increasing hepatic APP levels." (PMID 36187787, 2022). "Another gene associated with obesity found in our signature is the APP gene, which is upregulated in mitochondria and regulates mitochondrial function." (PMID 34572079, 2021). "Our study is the first study suggesting that exacerbated HFD-induced obesity and glycemic dysregulation in APP/PS1 transgenic mice are associated with impaired insulin and hypothalamic leptin signaling." (PMID 30096853, 2018). "On the other hand, it has been reported that amyloid protein precursor (APP) is related with inflammatory changes in brain and adipose tissue during obesity and is associated with insulin resistance." (PMID 28680065, 2017). "Because obesity could exacerbate the vascular inflammation likely underlying this neutrophil adhesion, we tested links between obesity and AD by feeding APP/PS1 mice a high fat diet (Hfd) and evaluating behavioral, physiological, and pathological changes." (PMID 32555372, 2020). "However, they were much more frequent in CAA-HF compared to all other groups, suggesting the greatest level of macrophage infiltration occurs in visceral fat of mice with mutated APP under diet-induced obesity (DIO) conditions." (PMID 22912823, 2012). "This study aimed to investigate the impact of Andro on glucose metabolism in VAT using a high-fat diet (HFD)-induced obesity model in AD mice (APP/PS1)." (PMID 40825507, 2025). "The associations of APP with metabolic diseases, including type 2 diabetes, obesity, non-alcoholic fatty liver disease, and cardiovascular disease, further support the extracerebral effects of APP." (PMID 38892548, 2024). "In concordance with studies of others, more pronounced HFD-induced obesity was observed in APP/PS1 mice, followed by increased amounts of the eWAT, resulting in elevated levels of plasma leptin, cholesterol, and TGs in 6- and 10-month-old mice." (PMID 37686722, 2023). "In this study, obesity-induced peripheral and central IR and inflammation were studied in relation to AD-like pathology in the brains and periphery of APP/PS1 mice, a model of Aβ pathology, fed a high-fat diet (HFD)." (PMID 37686722, 2023). "This study reveals a deleterious effect of obesity-related mild peripheral inflammation and prediabetes on the development of Aβ and Tau pathology and neuroinflammation in APP/PS1 mice." (PMID 37686722, 2023). "Our study aimed to determine a potential relationship between obesity-induced IR, inflammation in the periphery and AD-like pathology in the brains of APP/PS1 mice fed a HFD." (PMID 37686722, 2023). "Clearly, further studies will be needed to characterize the signaling pathways that modulate hepatic LRP-1 and APP in alcohol-induced and obesity-induced liver steatosis." (PMID 36187787, 2022). "Both obesity and alcohol intake have been linked to AD and our data suggests that liver steatosis associated with these two conditions modulates hepatic LRP1 and APP to disrupt Aβ processing by the liver to promote AD." (PMID 36187787, 2022). "Accordingly, miniature excitatory postsynaptic currents’ frequency was shown to be increased in neurons derived from APP-knockout mice, in which a resistance to an HFD-induced obesity was observed and linked to higher energy expenditure and lipid oxidation." (PMID 34228639, 2021). "It has been reported that accumulation of APP in mitochondria can impair mitochondrial function and lead to obesity, a potential driver of various cancers." (PMID 34151937, 2021).
Obesity (continued). "The mechanism of cellular obesity occurring during the middle-ages is strongly associated with decreased blood-brain barrier (BBB) integrity, tau phosphorylation, and decreased amyloid precursor protein (APP) levels." (PMID 35071357, 2021). "Concerning obesity and its influence on Aβ deposition, several studies have reported body weight gain in APP transgenic mice in response to high-calorie diets." (PMID 33384592, 2020). "We previously demonstrated that glycemic dysregulation and obesity are augmented in high fat diet (HFD)-treated APPswe/PS1dE9 (APP/PS1) transgenic mice." (PMID 30096853, 2018). "Cellularly, obesity during midlife has been associated with decreased BBB integrity, increased amyloid precursor protein (APP) levels, and increased tau phosphorylation." (PMID 30586872, 2018). "This study revealed that impaired leptin and insulin signaling mediated exacerbated obesity and glucose dysregulation through the interaction of the APP/PS1 genotype and HFD." (PMID 30096853, 2018). "Some experimental studies support the notion that HFD‐induced obesity exacerbates cerebral pathological alterations and the accompanying cognitive deficit in APP transgenic mice." (PMID 30079520, 2018). "Our findings demonstrate that APP expression is critical for the weight gain and adipose tissue hypertrophy that occurs in a murine model of high fat diet-induced obesity." (PMID 28262782, 2017). "In APP/PS1-ob/ob mice, an age-dependent excessive obesity was observed from 4 to 24 weeks of age compared with the APP/PS1 littermates (p < 0.01)." (PMID 28467789, 2017). "Since TNFα levels were increased under diet-induced obesity conditions in both adipose tissue depots, TNFα secretion was measured from APP stimulated adipocytes." (PMID 22276186, 2012). "This suggests that further investigation is needed to fully understand the role of APP in adipocyte biology both basally and during instances of increased APP expression such as that which occurs during diet-induced obesity." (PMID 22276186, 2012). "Although APP stimulation did not alter adipocyte phenotype in our hands a more extensive assessment would likely identify APP-dependent changes in adipocytes relevant to obesity." (PMID 22276186, 2012). "It has previously been shown that APP expression is upregulated in adipose tissue in response to obesity and APP knock-out mice have reduced body weight." (PMID 22912823, 2012). "Perhaps even more interesting is the possibility that APP dependent proinflammatory events contribute to the classic inflammatory changes commonly observed in peripheral adipose tissue during diet-induced obesity." (PMID 22276186, 2012). "This demonstrated that a coordinated, increased expression of APP occurred in the brain and adipose tissue upon diet-induced obesity along with acquisition of proinflammatory tissue phenotypes." (PMID 22276186, 2012). "Impaired insulin signaling in peripheral tissues, caused by HFD consumption that was even more pronounced in APP/PS1 mice, could lead to obesity and T2DM as a result of IR, as described in the study of Huang." (PMID 37686722, 2023). "Obesity was also accompanied by hyperinsulinemia of both genotypes at the ages of 6 and 10 months; in addition, 10-month-old APP/PS1 mice on a HFD reached insulin levels that were 38-fold higher than those of their controls on a STD and 3-fold higher than those of age-matched WT controls on a HFD." (PMID 37686722, 2023). "The fact that both alcohol feeding models (intragastric to mice and rats, NIAAA binge) and obesity caused the downregulation of LRP1 and upregulation of APP suggests that steatosis may be the uniting factor in the dysregulation of these two genes in the liver." (PMID 36187787, 2022). "The APP gene has also been reported to affect meat tenderness in pigs and obesity in humans." (PMID 27023061, 2016).
Obesity (continued). "This supports the idea that a particular function of APP may contribute to the metabolic changes that occur in each tissue during diet-induced obesity." (PMID 22276186, 2012). "However, APP is highly expressed in a variety of tissues including adipose tissue, where APP is also known to exhibit increased expression in response to obesity." (PMID 22912823, 2012). "Recent data suggests that APP expression or function may also be involved in the pathophysiology of obesity." (PMID 22276186, 2012). "In conditions which are obesogenic (excess calories, reduced energy expenditure), and that have altered expression of APP or APP processing components, there is likely a promotion of adiposity and exacerbation of obesity-induced metabolic dysfunction as the result of impaired adipose function." (PMID 22912823, 2012). "The specific contributions of APP to the complications of obesity remain largely undefined." (PMID 22912823, 2012). "At the very least, the APP changes observed may serve as one of the growing list of bio-markers that identify obesity-related changes." (PMID 22276186, 2012). "At the very least, unraveling the cell-specific function of APP in parallel with any proteolytic processing by adipocytes and macrophages during high fat diet feeding may offer insight into events that occur during obesity that may be extrapolated to AD." (PMID 28262782, 2017). "In this study a high fat diet-induced model of obesity was used with C57BL6/J mice to determine whether changes in APP expression occurred similarly in brain versus visceral and subcutaneous fat depots in correlation with simultaneous proinflammatory changes in each tissue." (PMID 22276186, 2012). "The study reveals significant metabolic changes in the VAT of obese APP/PS1 mice and highlights Andro's potential as a therapeutic agent for addressing VAT impairment induced by obesity in AD." (PMID 40825507, 2025). "HFD-induced obesity was related with growing age to a significant increase in CRP, a marker of peripheral inflammation, only in the fasted plasma of APP/PS1 mice at 6 and 10 months of age in comparison with 3-month old mice on a HFD." (PMID 37686722, 2023). "It is also important to note that the novel EC proteins, APP, CAD, BRD2 (which is part of DKFZp313H139), CST3, GRN, PPM1G and ZC3H4, have all been reported to be positively associated with obesity or adiposity, whilst the novel EC protein SLC25A24 may even prevent obesity and promote leanness." (PMID 37760635, 2023). "Untreated APP/PS1 mice weighed significantly more at 5–6 months of age than FK506-treated wild-type, treated APP/PS1, or control C57/Bl6 mice, suggesting FK506 prevented weight gain and obesity." (PMID 37849016, 2023). "In summary, the APP/PS1 mice fed a Hfd in this study broadly reproduced the phenotype of impaired behavior and increased brain inflammation that previous research on obesity and AD in mouse models has reported." (PMID 32555372, 2020). "A high fat diet-induced model of obesity was used with C57BL/6 wild type and APP−/− mice to define the requirement for APP in regulating adipose tissue hypertrophy and macrophage activation." (PMID 28262782, 2017). "This study identifies novel effects of mutant APP expression towards adipose tissue under obesogenic and non-obesogenic conditions, and provides a new model whereby peripheral expression of mutant APP could contribute to brain pathogenesis and the complications of obesity." (PMID 22912823, 2012). "Altogether, these data show that the CHOL diet induced hallmarks of NAFLD in the absence of the development of obesity in APP/PS1 mice." (PMID 31130652, 2019). "The biological role for APP in adipose tissue has not yet been well established, although APP is known to be increased in adipose cells in response to obesity in humans and mice." (PMID 22912823, 2012).
Obesity (continued). "Both APP/PS1 and WT mice fed HFD developed severe obesity compared to their age-matched controls on STD that did not significantly gain weight throughout the whole experiment." (PMID 37686722, 2023). "Amyloid precursor protein/presenilin-1 (APP/PS1) transgenic mice fed with a cholate, cholesterol, and high-fat diet is reported to induce NAFLD without hyperglycemia and obesity." (PMID 36143853, 2022).
frontotemporal dementia (45 papers, 2011 to 2025). Frontotemporal dementia (FTD) comprises a group of neurodegenerative disorders, characterized by progressive changes in behavior, executive dysfunction and language impairment, as a result of degeneration of the medial prefrontal and frontoinsular cortices. "Mutations in the Aβ precursor protein (APP) and a protease involved in Aβ production from APP strongly argue for a pathogenic role of Aβ in AD, while mutations in tau are associated with related disorders collectively called frontotemporal lobar degeneration (FTLD)." (PMID 24876993, 2014). "These include models overexpressing mutated human Aβ (such as 5xFAD and APP/PS1), commonly used to study AD, and a mutated human Tau strain (K257T/P301S) related to frontotemporal dementia (FTD)." (PMID 40794835, 2025). "BET protein inhibitor, JQ1, improved brain plasticity in wild-type and APP-expressing mice and rescued hippocampal-dependent cognitive deficits in a murine model of frontotemporal dementia." (PMID 40727583, 2025). "Recent work in a mouse model expressing both APP/PS1 and P301L mutant tau, which is associated with frontotemporal dementia, showed that reducing levels of mutant tau prevents neuronal loss." (PMID 31825838, 2019). "Most AD mouse models overexpress a mutated form of the human APP gene, a combination of mutated APP and PS1, or a combination of APP, PS1 and P301L (a tau mutation causing frontotemporal dementia)." (PMID 23126652, 2012). "In contrast, we did not observe differential expression of Alzheimer‐related genes mapta (encoding tau) or appa (encoding amyloid beta precursor protein), nor the frontotemporal dementia/amyotrophic lateral sclerosis gene tardbp (encodes Tdp‐43)." (PMID 38742929, 2024). "Transgenic rodent models of AD have been created and studied by overexpressing rare human mutations in the amyloid precursor protein (APP) and associated secretase components (Psen1 and Psen2) identified in early-onset FAD and tau mutations causal for frontotemporal dementia." (PMID 28560709, 2017). "In contrast to the APP gene, mutations in tau do not cause AD, but fronto-temporal dementia (FTD; Goedert and Jakes, 2005)." (PMID 25009496, 2014). "Additionally, JQ1 enhanced brain plasticity across various mouse models, including wild-type and APP-expressing mice, and effectively rescued hippocampal-dependent cognitive deficits observed in C9BAC mice, an animal model of frontotemporal dementia." (PMID 40305227, 2025). "In each of these tasks, the most frequently studied rodent models are amyloid models based on expression of mutant amyloid precursor protein (APP), presenilin and the phosphoprotein tau, followed by TDP-43 mutant mouse models (a model of ALS and frontotemporal dementia)." (PMID 37059739, 2023). "The most widely used transgenic models express mutant forms of the amyloid precursor protein (APP) gene, with or without presenilin-1/2 (PSEN1/2), which are associated with autosomal-dominant, early-onset AD, or, alternatively, MAPT mutations, which cause familial frontotemporal dementia (FTD)." (PMID 32668255, 2020). "In a previous study on frontotemporal lobar degeneration (FTLD) including a limited number of patients with ALS, we analyzed soluble non-amyloidogenic fragments of beta-amyloid precursor protein (APP), sAPPα and sAPPß which were suggested to protect neurons from proteasomal stress." (PMID 21858182, 2011). "While mutations in APP, PSEN1, and PSEN2 in the Aβ-generation pathway may lead to familial AD showing plaques and tangles, mutations in MAPT may lead to tangle formation but not plaques, resulting in frontotemporal dementia (FTD) or conditions similar to CBD, PSP, or PiD." (PMID 38732197, 2024).
epilepsy (39 papers, 2011 to 2025). A brain disorder characterized by episodes of abnormally increased neuronal discharge resulting in transient episodes of sensory or motor neurological dysfunction, or psychic dysfunction. "This disruption is magnified in the pathogenesis of epilepsy, as evidenced by the increased incidence of fatal seizures and reduced survival rate in APP/PS1 mice deficient in Ms4a4a." (PMID 40349168, 2025). "Data from a published cohort of patients (n = 171) with APP variants and concordant epilepsy indicate a prevalence of epilepsy of 20.3% in this group." (PMID 41551043, 2025). "In this study, we demonstrated that epilepsy susceptibility was upregulated in 4-month-old APP/PS1 mice compared with their WT littermates." (PMID 38388921, 2024). "Addressing the question if altered processing of APP and accumulation of amyloid-β in the brain are the cause or effect of epilepsy is of great importance." (PMID 37305553, 2023). "The prevalence of epilepsy was 60% in patients with APP duplication and 45% for those with PSEN1 mutation." (PMID 34121170, 2021). "The implicated contribution of amyloid peptides and/or APP metabolites, alone and even more when combined with mutant protein tau, in inducing neuronal hyperexcitability and epilepsy susceptibility is evident." (PMID 27259247, 2016). "In the examined autistic cohort, the early onset of intractable epilepsy and the epilepsy-related chronic and acute brain trauma appear to be additional risk factors for APP pathway activation and diffuse plaques formation." (PMID 22567102, 2012). "Given the variant’s proximity to known epilepsy-associated APP variants, and the patient’s seizure history, this case may contribute to the emerging genotype–phenotype correlation." (PMID 41551043, 2025). "Notably, at least one APP variant within the variant’s hotspot, p.Ala692Gly, has been reported to be associated with epilepsy." (PMID 41551043, 2025). "We sought to explore whether the administration of exogenous NRG1 could alter epilepsy susceptibility in APP mice." (PMID 38388921, 2024). "Taken together, these results suggested that APP mice are more susceptible to epilepsy than WT." (PMID 38388921, 2024). "Rescue of GABAergic inputs, such as regulating NRG1-ErbB4 signaling, may reduce the risk of epilepsy and intervene in the disease phenotype in APP/PS1 mice." (PMID 38388921, 2024). "Caveat: Is APP a cause or effect of epilepsy in microcephaly?" (PMID 37808474, 2023). "While the mechanisms for the convergence of histopathological features of AD and epilepsy brain samples remain elusive, growing data imply that neuronal hyperactivity associated with seizures can influence APP processing, as reflected in changes of Aβ isoforms and fragments of soluble APP in CSF." (PMID 36884195, 2023). "Epilepsy, associated with several genetic conditions, may also contribute to alterations in APP processing." (PMID 37808474, 2023). "Among patients with AD, the burden of epilepsy development is significantly higher for those with the inherited form of AD, which is associated with autosomal-dominant mutation of specific genes encoding the APP protein, PSEN1 and PSEN2." (PMID 34121170, 2021). "The results suggest that BACE1 (and APP) elevation, as well p-tau overexpression, could be potentially linked to aberrant synaptic/axonal plasticity in experimental epilepsy." (PMID 23155407, 2012). "There is a single case report of a 20-month-old male infant homozygous for an APP LOF variant who exhibited significant developmental delay, microcephaly, and severe epilepsy." (PMID 41123760, 2025). "For APOE we additionally tested for association with hyperlipidaemia and for APP and MAPT we tested for associations with mental health and epilepsy." (PMID 41123760, 2025). "The reduced expression of the Alg13 gene signifies that the epilepsy-related neuropsychiatric pathology was attenuated via the regulation of GABA receptors in the IGF-1-injected APP/PS2 mice." (PMID 38473814, 2024).